PDPN (podoplanin)
Diseases named in the same sentence as PDPN in open-access papers (continued):
Sharing a sentence is not in itself a finding about the gene and the disease.
glioma (continued). "We submitted the expression sequences of all glioma patients from TCGA to the TIDE website for analysis and found that PDPN expression was higher in those samples predicted by TIDE to respond to immunotherapy than in samples that did not respond." (PMID 36434176, 2023). "Another study calculated significant prognostic values for four hub genes (EMP3, PDPN, TAGLN2, and TIMP1) related to m6A regulators, all with high expression in high-grade glioma, and further correlation to IDH status and transcriptome subtype." (PMID 36831575, 2023). "We found that PDPN mRNA expression increased with the tumor grade, and the expression in IDH-wildtype (IDH-WT) gliomas of each grade was higher than that in IDH-mutant (IDH-Mut) gliomas." (PMID 36434176, 2023). "We also observed the cytolytic effect of Lp2-CAR-T cells on patient-derived glioma stem cells, GIC0222 and TGS01, both of which express cancer-type PDPN." (PMID 35991754, 2022). "We demonstrate that podoplanin (PDPN) expression is an independent prognostic marker in gliomas across multiple independent patient cohorts comprising both high- and low-grade gliomas." (PMID 36059614, 2022). "Expression of the type-I integral membrane glycoprotein podoplanin (PDPN), also known as OTS-8, PA2.26, gp36, gp38, RANDAM-2, T1-α, and aggrus, correlates with defining glioma stem cell characteristics." (PMID 36059614, 2022). "NZ-1-CAR T cells showed specific efficacy against PDPN-positive GBM cells in vitro and inhibited the growth of intracranial glioma xenografts in vivo." (PMID 35991754, 2022). "A series of genes such as EN1, S100A4, ANXA1, PDPN, IGFBP2 and CHI3L1 were upregulated in radiotherapy treated glioma patients, while other genes such as PRLHR, SFRP2, BRINP1, TRIM67, LHX5, KCNIP2 and NSG2 were downregulated." (PMID 34852024, 2021). "CD70, a member of the tumor necrosis factor receptor family, and podoplanin (PDPN), a type I transmembrane mucin-like glycoprotein, have also been recently identified as a CAR T cell target in glioma." (PMID 32903405, 2020). "Podoplanin (PDPN) is among the most frequently upregulated genes in squamous cell carcinoma, central nervous system tumors and germinal neoplasia." (PMID 26528756, 2015). "Some studies have reported that PDPN, CD133, and nestin expression are prognostic in glioma patients." (PMID 25580136, 2014). "Survival analyses further revealed that elevated PDPN expression was associated with worse overall survival specifically in the IDH-wildtype subgroup, whereas no significant prognostic effect of PDPN expression was observed in IDH-mutant gliomas." (PMID 40554484, 2025). "In addition, subgroup analyses demonstrated that PDPN expression was significantly higher in glioblastomas and IDH-wildtype gliomas compared to other subtypes." (PMID 40554484, 2025). "In comparison to other glioma subtypes, the GS2 exhibited higher expression levels of IBSP, PLA2G2A, NNMT, CA9, and MMP9, while the GS5 showed higher expression levels of CHI3L1, IGFBP2, EMILIN3, MEOX2, and PDPN." (PMID 38332637, 2024). "We investigated the prognostic significance of PDPN and its role in IME in glioma." (PMID 36434176, 2023). "However, the further mechanisms of PDPN in the regulation of the IME and tumor progression in glioma remain largely unclear." (PMID 36434176, 2023). "We demonstrated that this novel CAR-T cell was effective against glioma cells that express PDPN but did not have any cytolytic effect against PDPN-expressing non-cancer cells like mesothelial cells." (PMID 35991754, 2022). "The third-generation PDPN-redirected CAR-Ts were reported to mediate efficient anti-tumor responses against PDPN-positive GBM cell lines (LN319, U87MG) in vitro and inhibit r growth in a glioma mouse xenograft model." (PMID 36261831, 2022). "The study found that PDPN and TIMP1 can be used as prognostic factors for glioma." (PMID 34900988, 2021).
glioma (continued). "Furthermore, PDPN and TIMP1 were confirmed that they were higher expression in high-grade glioma and knockdown their expression decreased the glioma cell proliferation in vitro." (PMID 33123464, 2020). "Also, CAR-T cells directed to PDPN by a construct composed of NZ-1-based single-chain variable fragments and CD28, 4-1BB and CD3 ζ intracellular domains have shown good efficiency against glioma cells both in vitro and in vivo glioma xenografts." (PMID 40677711, 2025). "More specifically, given this apparent lack of distribution of PDPN around the perivascular niche, future studies may aim to understand how oxygen tension, or hypoxic conditions, may regulate PDPN biology in glioma." (PMID 36059614, 2022). "The PDPN and TIMP1 may serve as potential biomarkers for prognosis of glioma." (PMID 33123464, 2020). "Moreover, we also found PDPN and TIMP1 were highly expressed in high-grade glioma from The Human Protein Atlas database and both of them were correlated with m6A and immune cell marker in glioma tissue samples." (PMID 33123464, 2020). "Furthermore, peripheral lymphoid tissues harbored a PDPN+ myeloid subpopulation in presence but also in absence of glioma growth." (PMID 30972297, 2019). "Interestingly, CD11b+ PDPN+ cells were only present in glioma-bearing brains but not in unchallenged brain tissue." (PMID 30972297, 2019). "In contrast to BMDM and spleen macrophages that both comprise a PDPN+ subpopulation at any condition, we could not detect PDPN protein on microglial cells, suggesting that the PDPN+ myeloid cell type we found in glioma tumors are not activated microglia." (PMID 30972297, 2019). "Here, we detected PDPN+ myeloid cells in glioma tumors, however, not in untreated brains." (PMID 30972297, 2019). "This investigation validated the heightened expression of PDPN in astrocytes triggered by glioma growth and brain ischemia, suggesting that PDPN could be a novel cell surface marker for a distinct group of reactive astrocytes near gliomas and non-neoplastic brain lesions." (PMID 39682237, 2024). "In addition, PDPN and TIMP1 were found to be highly expressed in high-grade glioma via The Human Protein Atlas database, and both correlated with m6A and macrophage marker CD68 in glioma tissue samples, which may serve as potential biomarkers for glioma prognosis." (PMID 38071304, 2023). "In human glioma cells lacking PTEN, reintroduction of wild-type PTEN, inhibition of PI3-kinase by LY294002, or inhibition of AP-1 activity by dominant-negative JUN and FOS resulted in potent downregulation of PDPN expression." (PMID 35159384, 2022).
squamous cell carcinoma (58 papers, 2007 to 2025). A carcinoma arising from squamous epithelial cells. "The strong podoplanin expression was associated with post-operative radiotherapy (p = 0.004) in those patients diagnosed with squamous cell carcinomas." (PMID 29310601, 2018). "PDPN is upregulated in a variety of cancers, including squamous cell carcinomas (SCCs) and glioblastomas, generally associated with poor prognosis." (PMID 26893367, 2016). "Here, we uncover a new role for podoplanin, a transmembrane glycoprotein closely associated with malignant progression of squamous cell carcinomas (SCCs), in the regulation of invadopodia-mediated matrix degradation." (PMID 25486435, 2015). "The expression of podoplanin in human squamous cell cancers and its association with cancer cell motility suggest a possibility that it could be used as a biomarker to predict lymph node metastasis." (PMID 36247509, 2022). "Lymphatic markers like VEGFR-3 and PDPN, while useful in identifying subsets of AS, are inconsistently expressed across AS cases, with PDPN also detectable in squamous cell carcinomas and seminomas." (PMID 40666093, 2025). "Assessing the distribution of each marker across different tissue classes revealed differences between adenocarcinoma and squamous cell carcinoma, notably the expression of PDPN being higher in squamous cell carcinoma." (PMID 38582812, 2024). "PDPN expression is increased in many neoplasms like angiosarcoma, lymphangioma, and squamous cell carcinomas of the oral cavity, skin, esophagus, lung, larynx, and cervix." (PMID 37273383, 2023). "PDPN expression is upregulated in various malignancies such as squamous cell carcinomas of the oral cavity, larynx, skin, lung, esophagus, and cervix, colorectal adenocarcinomas, and testicular germ cell tumors." (PMID 37273383, 2023). "Overexpression of PDPN has been reported in many tumors, including squamous cell carcinomas in the head and neck, esophagus, malignant gliomas, and mesotheliomas, and is associated with poor clinical outcomes." (PMID 37894446, 2023). "Wound healing assays have also demonstrated the invasive property of podoplanin through interaction of VEGF-C in squamous cell carcinomas." (PMID 36247509, 2022). "In the previous studies, authors have reported that podoplanin expression was found at the invasive front of the tumor in more than 80% of human squamous cell carcinomas." (PMID 36247509, 2022). "Podoplanin (PDPN), a type I transmembrane mucin-like glycoprotein, is abundant in several solid tumors including squamous cell carcinoma, malignant mesothelioma, Kaposi sarcoma, angiosarcoma, testicular seminoma, and brain tumors." (PMID 35991754, 2022). "With the advent of recent studies, podoplanin has been found in several carcinomas like squamous cell carcinoma, mesothelioma, and germ cell tumors." (PMID 36247509, 2022). "PDPN is highly expressed in many types of cancer, such as brain tumors, squamous cell carcinoma, soft tissue tumors, and bladder cancer." (PMID 34685483, 2021). "Podoplanin, a transmembrane glycoprotein related to the progression of human squamous cell carcinoma, was also increased in the presence of butyrate for HSC-2 and HSC-3 cell lines." (PMID 32664466, 2020). "Podoplanin expression is upregulated in a number of different human cancers, including germ cell tumors, tumors of the central nervous system and squamous cell carcinomas (SCCs) of the oral cavity, skin and the lung." (PMID 32599908, 2020). "In human medicine, PDPN has been reported to be overexpressed in various types of tumors, including squamous cell carcinoma, astrocytoma, malignant mesothelioma, hemangiosarcoma, osteosarcoma, germinoma, and cancer-associated fibroblasts (CAFs)." (PMID 33238582, 2020). "PDPN is also upregulated in a variety of neoplasms, including colorectal tumors, squamous cell carcinomas, mesothelioma, testicular seminoma, brain tumors and some types of vascular tumors as well as in some papillary thyroid tumors." (PMID 30654768, 2019).
squamous cell carcinoma (continued). "PDPN overexpression is also observed in different types of tumors, including mesotheliomas, squamous cell carcinomas (SCC), testicular tumors, and glioblastomas." (PMID 30519645, 2019). "Podoplanin overexpression has been detected in wide range of tumor cells, including squamous cell carcinoma, mesothelioma, glioblastoma, bladder cancer, angiosarcoma, brain tumors, testicular seminoma, and osteosarcoma." (PMID 30279963, 2018). "PDPN is often up-regulated in cancer, particularly in squamous cell carcinomas, such as cervical, skin and lung cancers and plays a key role in cancer cell invasiveness by controlling invadopodia." (PMID 30544833, 2018). "Key words:Immunohistochemistry, Oral leukoplakia, Oral submucous fibrosis, Podoplanin, Squamous cell carcinoma." (PMID 29410757, 2017). "It is well known that PDPN expression is increased in various malignant tumors including squamous cell carcinomas." (PMID 28059107, 2017). "PDPN is a lymphatic endothelial marker and among the most frequently up-regulated genes in squamous cell carcinoma, central nervous system tumors and germinal neoplasia." (PMID 29100400, 2017). "Various types of tumor cells also express podoplanin such as vascular tumors, central nervous system, germ cell tumors and squamous cell carcinoma." (PMID 29410757, 2017). "We previously reported that podoplanin is a TIC-specific marker for the human squamous cell carcinoma cell line A431." (PMID 28059107, 2017). "Our study confirmed that PDPN was a potential biomarker to identify the presence of early infiltrative squamous cell carcinoma." (PMID 28086225, 2017). "According to their observations, podoplanin positive CAFs predicted poor survival and outcome among lung adenocarcinoma and squamous cell carcinoma patients, whereas in small cell lung cancer podoplanin positivity suggested better prognosis." (PMID 26798356, 2016). "The amount of EXOs produced by human HN5 squamous carcinoma cells after PDPN knockdown by small hairpin RNA (shRNA) interference was also quantified." (PMID 26893367, 2016). "In lung adenocarcinoma and squamous cell carcinoma, we considered CAFs-expressing PDPN to be a stromal cell component with a tumor-promoting phenotype." (PMID 25909164, 2015). "Podoplanin is abnormally expressed in the early oral tumorigenesis and identified as a new marker for tumor initiating cells in squamous cell carcinoma." (PMID 26558136, 2015). "Our evidence of the pro-invasive character of high PDPN expression contrasts with reports showing that low expression of PDPN correlates with poor prognosis, e.g. in squamous cell carcinoma of lung, and uterine cervix cancer." (PMID 24797369, 2014). "An increased level of PDPN was reported in highly metastatic clones of mouse colon adenocarcinoma and melanoma cell lines and in approximately 80% of human squamous cell carcinomas of the lung, larynx, cervix, skin, and oesophagus." (PMID 24797369, 2014). "Podoplanin is found in various neoplasms, such as squamous-cell carcinoma, germ cell tumors, mesothelioma, and some subtypes of vascular tumors." (PMID 24804195, 2014). "PDPN overexpression was identified as a pro-metaststic factor in squamous cell carcinoma, larynx and oesophagus tumors, and tumors of the central nervous system." (PMID 24797369, 2014). "In fact, podoplanin has been identified as a marker of tumour-initiating cells (TICs) in squamous cell carcinomas." (PMID 20196862, 2010). "We have recently reported that in about 80% of human squamous cell carcinomas (lung, larynx, cervix, skin and oesophagus) podoplanin is expressed – often in a one-cell layer – at the invasive edge of the tumours." (PMID 17179989, 2007). "Podoplanin expression is mainly detected in squamous cell cancers, CNS tumours and germinal neoplasia." (PMID 17179989, 2007).
squamous cell carcinoma (continued). "Recently, we have shown that in human squamous cell cancer, but also in an animal model of insulinoma, podoplanin is involved in a pathway of collective cell migration and invasion, which is independent from EMT." (PMID 17179989, 2007). "The Podoplanin (PDPN) is a transmembrane sialo-glycoprotein and its overexpression has been detected in many types of tumors, including squamous cell carcinoma, malignant mesothelioma, esophagus, Kaposi’s sarcoma, testicular seminoma and brain tumors, and is associated with poor clinical outcomes." (PMID 38561690, 2024). "PDPN expression also showed significant difference in expression levels between adenocarcinoma and squamous cell carcinoma, showing higher percentage positivity of PDPN in squamous cell carcinoma patients." (PMID 38582812, 2024). "Furthermore, PDPN mediates the diverse pattern of tumor invasion, including collective invasion in squamous cell carcinomas and ameboid invasion in melanoma." (PMID 37894446, 2023). "Using the combination of pan-cytokeratin, EGFR, β-catenin, Ki67, and podoplanin, a candidate cancer stem cell marker in squamous cell carcinoma, the highly proliferating and less differentiated tumor cells at the periphery of the tumor islet can be distinguished." (PMID 33936105, 2021). "In addition to its role in human cancers, PDPN is also overexpressed in canine squamous cell carcinomas and melanomas and PDPN mAbs were recently found to have potent anti-tumor activity in mouse xenograft models of canine melanoma." (PMID 32571313, 2020). "Similar to humans, PDPN has been reported to be expressed in renal podocytes, alveolar epithelial cells, and lymphatic endothelial cells of dogs, and in various types of canine tumors, including malignant melanoma and squamous cell carcinoma." (PMID 33238582, 2020). "Podoplanin was identified as a marker of tumor-initiating cells in squamous cell carcinomas." (PMID 30823625, 2019). "In this regard, PDPN has been identified as a marker for tumor-initiating cells (TIC) in squamous cell carcinomas, and PDPN-positive cells beyond the basal layer of the oral epithelium have been interpreted as an upward clonal expansion of stem cells during carcinogenesis." (PMID 31484317, 2019). "•Dog PDPN is expressed in canine squamous cell carcinomas and melanomas." (PMID 30519645, 2019). "Moreover, Martín-Villar and collaborators showed that PDPN contributes to both directional migration of normal epithelial cells and cells derived from squamous cell carcinomas (SCC)." (PMID 30654768, 2019). "They proposed that podoplanin activity may be a therapeutic target for the treatment of squamous cell carcinomas." (PMID 31321241, 2019). "Recently, PDPN was also found to be upregulated in a variety of tumors such as vascular tumors, malignant mesothelioma, tumors of the central nervous system (CNS), germ cell tumors, and squamous cell carcinomas." (PMID 31321241, 2019). "Thus, PDPN expression probably reflects a less mature status in the differentiation progress of squamous cell carcinomas." (PMID 28059107, 2017). "Indeed, expression of PDPN in MDCK cells stimulated both EXO and MV production, while knockdown of endogenous PDPN in human HN5 squamous carcinoma cells reduced EXO production and inhibited tumorigenesis." (PMID 26893367, 2016). "Similarly, human HN5 squamous carcinoma cells, which express endogenous PDPN, released full-length PDPN into the CM." (PMID 26893367, 2016). "Therefore, we considered CAFs expressing PDPN to represent a tumor-promoting component in adenocarcinoma and squamous cell carcinoma." (PMID 25909164, 2015). "In the present study, podoplanin positive cells were specifically located in most cases at the basal region of squamous cell carcinoma nests, close to the surrounding stromal cells, at invasive front, and the expression of podoplanin increases from well to poorly differentiated OSCC." (PMID 26558136, 2015).